CD4 (CD4 molecule)
Diseases named in the same sentence as CD4 in open-access papers (continued):
Sharing a sentence is not in itself a finding about the gene and the disease.
autoimmune disease (continued). "Rheumatoid arthritis (RA) is a complex autoimmune disease with multiple etiological factors, among which aberrant memory CD4 T cells activation plays a key role in the initiation and perpetuation of the disease." (PMID 36401167, 2022). "In the present study, we will summarize the current understanding of glutamine catabolism in CD4+ T-cell subsets of autoimmunity, and we will also discuss potential treatments targeting glutaminolysis in patients with autoimmune diseases." (PMID 36211442, 2022). "In HLA-class I-associated autoimmune diseases these are the CD8+ T cells, for HLA-class II-associated autoimmune pathology CD4+ T cells." (PMID 36700227, 2022). "CD4+ regulatory T (Treg) cells represent differentiated CD4+ T cells that are transcribed by Foxp3, mediate immunosuppressive function and prevent the emergence of deleterious autoimmune diseases." (PMID 36225914, 2022). "T helper (Th)-like DN T cells secrete cytokines, including interleukin (IL)-4, IL-17, interferon-γ (IFN-γ) and tumor necrosis factor-α (TNF-α), and play a similar role to CD4+ Th cells in infection and autoimmune disease." (PMID 35222392, 2022). "CD4+CD25−Foxp3+ T cell subsets were first described in peripheral blood of patients with autoimmune diseases." (PMID 36376825, 2022). "Targeting the dysfunctional metabolism of CD4+ T cells to treat autoimmune disease has aroused widespread concern in recent decades." (PMID 35211629, 2022). "Accumulation of intracellular lipid (cholesterol-containing) droplets in CD4+ T cells, coexisting with elevation of serum triglycerides and cholesterol, was observed in many autoimmune diseases, including rheumatic arthritis, SLE, and psoriasis." (PMID 35935991, 2022). "Antigen-specific B cells induce naïve CD4 + cell proliferation in vivo, and the role of B cells as APCs in autoimmune disease was proven." (PMID 35239103, 2022). "The interactions of CD4+ T cells and B cells are fundamental for the generation of antibody responses, as well as for the development of harmful autoimmune diseases." (PMID 35720293, 2022). "The fourth type of CD4+ cells, called regulatory T (Treg) cells, inhibits the effector action of CTLs and performs essential physiological functions in preventing autoimmune disorder, and intensifies immunity from infections." (PMID 35093033, 2022). "CD4+ effector T cells, especially IL-17-secreting Th17 cells, are critical in autoimmune disorders, whereas Treg cells mediate the maintenance and tolerance of autoimmunity." (PMID 36195600, 2022). "Tr1 cells and Foxp3+ regulatory T cells are highly immune‐suppressive subsets of CD4+ T cells, and they exert important suppressive and homeostasis effects on cancer, autoimmune disorders, and inflammatory responses." (PMID 35587519, 2022). "While Tregs play an important role in preventing autoimmune diseases, Tregs can regulate the adaptive immune system by regulating CD4 Th cells, CD8 T cells and B cells." (PMID 36462500, 2022). "Lymphocytic thyroiditis is an autoimmune disorder characterized by the activation of CD4+ T cells, which recruit many auto-reactive B cells which secrete various autoantibodies." (PMID 35573548, 2022). "Similar to tumour cells, glutamine metabolism is an absolute requirement of activated CD4+T cells, which play a key role in autoimmune disease including RA." (PMID 34698439, 2022). "IBD is an autoimmune disease involving both autoantibodies and autoreactive CD4-positive T-lymphocytes." (PMID 35795556, 2022). "These mice generated spontaneous autoimmune disease in what, at the time, was believed to be due to unimpeded CD4+ Tfh differentiation." (PMID 35493515, 2022). "Th22 cells, a new type of characterized CD4 + T cells with IL22 as the main cytokines, are associated with the pathogenesis of autoimmune diseases." (PMID 35756043, 2022).
autoimmune disease (continued). "T helper 17 (Th17) cells, which are a subpopulation of CD4+ T lymphocytes, are involved in the pathogenicity and immunoprotective mechanisms in various autoimmune diseases, such as inflammatory bowel disease, multiple sclerosis, and rheumatoid arthritis." (PMID 36570798, 2022). "From this perspective, thymic PCs would produce autoreactive antibodies, but it is unlikely that these antibodies would induce autoimmune disease as their affinity is low, and cognate CD4 T cells are eliminated while Tregs are selected." (PMID 35301301, 2022). "Follicular helper T cells are a distinct subset of CD4+ helper T cells that activate B cells, generate specific antibody responses, and play important roles in the progression of autoimmune diseases." (PMID 36591255, 2022). "The IL-17 family includes pro-inflammatory cytokines of whom IL-17A is a marker of a specific CD4+ T cell subset named CD4+ T helper 17 (Th17) and is involved in autoimmune diseases as well as infections." (PMID 36613822, 2022). "In fact, it is expected that a new type of self-reactive CD4 helper T lymphocytes proliferates, which would give rise to autoimmune diseases more easily." (PMID 36362500, 2022). "Treg cells are a distinct subset of CD4 + T cells that prevents abnormal or excessive immune responses and development of autoimmune disorders." (PMID 36581745, 2022). "Although many studies reveal the roles of CD4+ T cells in the development and pathogenesis of autoimmune diseases, its mechanisms remain to be elucidated during pathological processes." (PMID 35095344, 2022). "Herein, we review the mechanisms through which salt exacerbates autoimmune diseases via SGK1-induced signaling in CD4+ T cells." (PMID 36457711, 2022). "The role of CD4 T regulatory cells is well established in peripheral tolerance and the pathogenesis of the murine model and human autoimmune diseases." (PMID 35669770, 2022). "The most recognized role of statin is to promote the differentiation of CD4+ T cells into Th2, whereas to inhibit that into Th1 and Th17 in inflammation or autoimmune diseases." (PMID 35720273, 2022). "The CeD-associated CD4+ T cells express high levels of CD39, which is in accordance with previous studies showing their involvement in autoimmune diseases including CeD61,68." (PMID 35995787, 2022). "Multivariate logistic regression analysis of significant variables showed that CD4/CD8 ratio (OR 1.409, 95% CI 1.045–1.901) and autoimmune disease (OR 0.264, 95% CI 0.133–0.524) are independent risk factors for BE/PE patients, compared with the BE patients." (PMID 35681174, 2022). "During 1970-1980, many efforts were made to detect CD4+ T cells able to suppress autoimmune diseases in rodents through reliable molecular markers." (PMID 36591309, 2022). "Treg, an immunosuppressive subset of CD4+ T cells, is a potential therapeutic approach to autoimmune diseases, such as systemic lupus erythematosus, multiple sclerosis, and inflammatory bowel disease." (PMID 36310865, 2022). "CD4+ T cells contribute to the pathogenesis of autoimmune diseases such as rheumatoid arthritis (RA)." (PMID 35444834, 2022). "IL-17A producing cells including Th17 cells (IL-17A producing CD4+ T helper cells) are involved in human cancers and autoimmune diseases." (PMID 35902909, 2022). "On the other hand, cluster 7 cells displayed uniquely high expression of Slamf7, Eomes, and Gzmk, and as such, cells within this cluster bore a resemblance to a cytolytic CD4+ T cell subset that has been identified in tumors as well as autoimmune disease." (PMID 36255051, 2022). "T cell exhaustion is defined by successive upregulation of inhibitory receptors on CD8 and CD4 T cells in the presence of chronic antigen stimulation in cancer, infection, and autoimmune disease." (PMID 36314014, 2022).
autoimmune disease (continued). "Tregs, a subpopulation of CD4+ T cells, suppress immunity by secreting cytokines that suppress effector T cells, maintain immune homeostasis and prevent the development of autoimmune diseases." (PMID 36118855, 2022). "CD4+ effector T cells (Teff) are the major drivers of chronic inflammatory or autoimmune diseases including inflammatory bowel disease (IBD) and rheumatoid arthritis (RA)." (PMID 35990633, 2022). "Low CD4 + T cell counts characterize idiopathic CD4 + T lymphocytopenia and commonly presents as various opportunistic infections, autoimmune diseases, and/or neoplasias." (PMID 35248113, 2022). "ITP is an autoimmune disease, in which auto-reactive CD4+ T cells are thought to play pivotal roles in helping B cells to produce auto-reactive antibodies." (PMID 36233533, 2022). "Most investigators have noted the cooccurrence of these classic autoimmune disorders, as they share a similar pathogenetic process: the overactivation and hyperproliferation of CD4+ T cells." (PMID 35211629, 2022). "In fact, CD4+ T cells have been shown to play detrimental roles in many autoimmune diseases, including SLE, Sjögren's syndrome, Hashimoto's thyroiditis, and systemic sclerosis." (PMID 35095344, 2022). "MS is considered an autoimmune disease of the CNS, in which immune responses mediated by autoreactive CD4+ T cells seem to play a crucial role." (PMID 35185762, 2022). "Another T-cell subset, CD4+ T cells play a pivotal role in the adaptive arm of the immune system to regulate infections, transplantations, autoimmune diseases, and cancer development." (PMID 36005179, 2022). "CD4+ Th cells have been shown to play key roles in many autoimmune diseases and cancer immunotherapy." (PMID 35935994, 2022). "Naïve CD4+T cells can differentiate into a variety of Th cell subsets and play various roles in autoimmune diseases." (PMID 36524110, 2022). "In autoimmune disease, self-reactive Th17 cells differentiate from naïve CD4+ T cells via self-antigens presented by DCs in lymph nodes." (PMID 36570798, 2022). "Several other investigators have reported an association between reduced CD4 Tregs and CVID with autoimmune diseases." (PMID 35669770, 2022). "The role of CD4+CD25+Foxp3+ regulatory T (Treg) cells in abating the development of autoimmune diseases has been an area of intense study in recent years." (PMID 35563702, 2022). "It was obvious that bulk CD4+ T cells differentiated into Th1 and Th2 subsets during autoimmune diseases progression." (PMID 36457713, 2022). "Autoimmune disease or increased CD4/CD8 ratio likely has a predictive value for the diagnosis of bronchiectasis patients complicated with pulmonary embolism." (PMID 35681174, 2022). "Loss of Foxp3 expression or function can lead to the development of autoimmune diseases, while ex vivo generated iTregs from Foxp3-negative CD4+ Teff cells exhibit the suppressive and phenotypic characteristics like nTreg." (PMID 36500570, 2022). "On the other hand, autoimmune diseases are characterized by their excessive and dysregulated effector CD4+ T cell responses." (PMID 36418318, 2022). "Elevated proportions of memory CD4+ T cell subsets are also seen in autoimmune diseases such as multiple sclerosis and psoriasis where these T cells are repeatedly activated by autoantigens and therefore undergo expansion." (PMID 35837411, 2022). "Studies conducted in recent decades have pointed out that in a subset group of CD4+ T cells, regulatory T cells were a key modulator of allograft rejection for maintaining self-tolerance and preventing autoimmune disease." (PMID 35453586, 2022). "Other CD4+CD8αβ+ double-positive T cells do exist at low frequency in the periphery alongside conventional CD4+ and CD8+ T cells, and they have been linked to conditions such as infections, autoimmune diseases and cancer." (PMID 35222424, 2022).
autoimmune disease (continued). "CD4+ Th17 cells have been active in removing extracellular bacteria and autoimmune diseases, such as experimental autoimmune encephalomyelitis (EAE) and collagen-induced arthritis." (PMID 35093033, 2022). "IL-12 induces naive CD4+ T cells to differentiate into Th1 cells, a subset of T-helper cells involved in the etiology of many autoimmune diseases in humans." (PMID 35626130, 2022). "There is growing evidence that CD4+ T cells play a central role in the initiation and maintenance of the immune response against cancer or autoimmune diseases." (PMID 36090896, 2022). "This phenomenon is particularly well studied in autoimmune disease, cancer and infection where Th17 cell conversion into Th1 cells is critical for the overall CD4 effector response." (PMID 35835905, 2022). "In fact, the T-cell-mediated immune response plays a role in the pathogenesis of MS, which is recognized as a CD4+ T-cell-mediated autoimmune disease." (PMID 35955792, 2022). "Autoimmune diseases are marked by both cellular and humoral immune reactions that involve CD4+, Th1, Th17, and NK cells." (PMID 35736648, 2022). "CD4+T cells are irreplaceable regulators of autoimmune diseases; however, the detailed mechanism of their function in the immunopathology of pSS is still unclear." (PMID 35755031, 2022). "Regulatory CD4+ T (Treg) cells play a key role in the induction of immune tolerance and in the prevention of autoimmune diseases." (PMID 36569866, 2022). "mTORC1 and mTORC2 can also promote differentiation of TFH cells, another specialized CD4+ T subset involved in the pathogenesis of autoimmune diseases." (PMID 36311777, 2022). "Similar to PD-1, TIGIT, a novel immune checkpoint, which is mainly expressed on NKs, CD8+ T cells, CD4+ T cells, and Treg cells, is well known for its important role in tumor immunity and autoimmune diseases." (PMID 36426354, 2022). "This was supported by the finding that depletion of CD4+ T cells in these mice prevented the onset of the autoimmune disease and thus improved survival." (PMID 35493515, 2022). "Sakaguchi lab showed that, transfer of suspensions of CD25+ population-depleted T cells into athymic nude mice produced autoimmune disease, while co-transfer with CD4+ CD25+ T cells prevented the autoimmune disease." (PMID 35874688, 2022). "Despite the main source of IL-17A being Th17 CD4+ αβ T cells, γδ T cells also contribute to IL-17A production in autoimmune diseases." (PMID 36499125, 2022). "It has been shown that tregitopes have therapeutic effects on mouse models of autoimmune diseases through expansion of CD4 + CD25 + FOXP3 + Tregs37,41." (PMID 36418333, 2022). "Accumulated evidence has revealed that CD4+ CTLs play an important role in various pathologic conditions such as infectious diseases, autoimmune diseases, and cancers." (PMID 36077655, 2022). "EAE is a CD4+ T lymphocyte-mediated demyelinating autoimmune disease of the CNS, characterized by widespread central inflammation and infiltration of T cells and monocytes into the CNS." (PMID 34602975, 2021). "Although USP12 activated CD4+ T cell responses against bacterial infections, it also promoted autoimmune disease development." (PMID 33941870, 2021). "Cytotoxic CD4+ T cells (CD4 CTL) are terminally differentiated T helper cells that contribute to autoimmune diseases, such as multiple sclerosis." (PMID 34073458, 2021). "Although unconventional, this phenotype of CD4+ T cells has been detected in infection models and autoimmune diseases with potently suppressive capacities in mucosal inflammation." (PMID 34712620, 2021). "Based on this cumulative evidence of the significance of GM-CSF-producing CD4 T cells in human autoimmune disease, understanding the factors driving and defining GM-CSF-positive T cells would be of utmost importance for targeting them therapeutically." (PMID 34285924, 2021).
autoimmune disease (continued). "Th17 and Th22 proinflammatory cells, implicated in the pathogenesis of many autoimmune diseases, cancer and more, are a very minor part of the CCR4+ CD4 cells and are CD45R0." (PMID 34680079, 2021). "CD4+ T cells play a vital role in the adaptive immune system and are involved in the pathogenesis of many diseases, including cancer, autoimmune diseases, and chronic inflammation." (PMID 33505215, 2021). "Allelic variation of CTLA4 as well as CTLA4 blockade/anti-CTLA4 treatment influences the signaling threshold of CD4 T-cells, thereby augmenting antitumor immunity but also exacerbating/inducing autoimmune disease." (PMID 32089545, 2021). "Despite these advancements, the αβTCR-repertoire of autoreactive CD4 + T cells in many autoimmune diseases including rheumatoid arthritis has remained less understood, with the exception of celiac disease." (PMID 34972837, 2021). "The immunology of pregnancy is related to CD4+ T cell cytokines and T cell responses in autoimmune disease are influenced by pregnancy." (PMID 34441010, 2021). "Memory CD4+ T-cells are highly relevant to autoimmune diseases because of their long-lived nature, efficient responses to antigens, and specific potential to mediate recurring autoimmune responses." (PMID 33936039, 2021). "CD4+CD25− T cells appear to induce the development of autoimmune disease, while CD4+CD25+ cells tend to inhibit the development of disease." (PMID 34055193, 2021). "OWAS segments for RA marked genes specifically expressed in CD4+ T cells (P = 3.0e–07) and CD19+ B cells (P = 7.0e–06), and these two cell types are both associated with autoimmune diseases." (PMID 34260700, 2021). "CD4+ CAR-Tregs are also being investigated as an intervention for organ-specific autoimmune diseases in mice." (PMID 33854514, 2021). "In all three autoimmune disease models studied, the proportion of CD4+CD8-YFP+ cells in the draining lymph node was comparable between WT and Foxp3Cre-YFPmiR-21f/f mice." (PMID 34858422, 2021). "Our results provide for the first time evidence for differential expression of several MHC Class II genes in whole blood, PBMCs, CD4+ T cells, CD8+ T cells, and CD14+ monocytes of individuals with genetic predisposition to an autoimmune disease, i.e. RA." (PMID 34484204, 2021). "IL-17A is produced predominantly by CD4+ Th17 cells in response to cytokine IL-23 and plays an important role in various autoimmune diseases, including uveitis." (PMID 34356895, 2021). "The adoptive transfer of expanded autologous CD4 Tregs has been used to treat various autoimmune diseases, graft versus host disease and to prevent solid organ graft rejection." (PMID 34211471, 2021). "CD4 Tregs are involved in the regulation of various autoimmune diseases but believed to be highly heterogeneous." (PMID 34054801, 2021). "Th17 cells correspond to a subset of CD4+ T cells known to play a central role in the pathogenesis of many autoimmune diseases, as well as in the defense against some extracellular bacteria and fungi." (PMID 34552885, 2021). "In another study, after isolating CD4+ T cells from patients with MS and colitis, both autoimmune diseases, Tim‐3 expression and signal transduction defects were observed." (PMID 33728805, 2021). "A central role for CD4+ T-cells is seen in many autoimmune disorders, e.g., in celiac disease and type 1 diabetes." (PMID 33863907, 2021). "The addition of 1,25(OH)2D3 has direct effects on CD4+ T cells and supports its potent immunosuppressive benefits in the treatment of a number of other autoimmune diseases." (PMID 34414198, 2021). "Due to the high pathogenicity of CD4-producing IL-17 T cells in autoimmune diseases, a considerable effort has been made to elucidate their regulatory molecules and pathways." (PMID 34298735, 2021).